GATA4 (GATA binding protein 4)
Diseases named in the same sentence as GATA4 in open-access papers (continued):
Sharing a sentence is not in itself a finding about the gene and the disease.
tumor (continued). "In parallel, based on the Cancer Hallmarks Gene Set, these same genes were associated with processes such as evading immune destruction, tumor-promoting inflammation, sustained angiogenesis, and tissue invasion and metastasis, particularly through the actions of CLDN23 and GATA4." (PMID 40863222, 2025). "Genes such as GATA4, CLDN23, MICB, MFHAS1, and BMPR2 were enriched in multiple signatures including estrogen response, coagulation, DNA repair, tumor-promoting inflammation, immune evasion, angiogenesis, sustained proliferative signaling, resistance to cell death, and metastasis." (PMID 40863222, 2025). "For example, GATA4 has a tumor-suppressive effect in lung cancer, where it is not normally expressed." (PMID 39456519, 2024). "Some of the most notable dif-ferentially-expressed genes, however, included GATA4, a tumor suppressor that was downregulated and is a negative regulator of survival and a prognostic marker." (PMID 37881491, 2023). "We observed that GATA4, AGR2, and PPARG were significantly underexpressed in tumor samples." (PMID 35069736, 2022). "Cell cycle and mitotic pathways were not included in the top differentially expressed pathways, again suggesting that cellular proliferation is not the primary driver of Gata4-dependent tumor suppression." (PMID 35017504, 2022). "Gata4 overexpression combined with anti-PD-1 antibody led to tumor suppression that was not statistically different from GVAX combined with anti-PD-1 antibody." (PMID 35017504, 2022). "Flow cytometric analysis of the tumors showed that the percent of tet-Gata4 cells in each tumor remained constant throughout the experiment rather than depleting relative to tet-GFP cells." (PMID 35017504, 2022). "Taken together, these data suggest that inactivation of the SASP regulator Gata4 enhances tumorigenesis by increasing tumor initiation rather than by increasing cell proliferation." (PMID 35017504, 2022). "Gata4 overexpressing cells were not depleted relative to control tumor cells in the same tumor, revealing that Gata4 does not function to regulate the cell cycle in a cell-autonomous manner." (PMID 35017504, 2022). "Importantly, Gata4 required an intact adaptive immune system, specifically CD8 cytotoxic T cells, in order to suppress tumor growth." (PMID 35017504, 2022). "Here the authors show that GATA4’s pro-inflammatory secretome promotes the recruitment of immune cells such as CD8 + T cells to suppress tumour initiation and growth in a non-cell autonomous manner." (PMID 35017504, 2022). "Thus, GATA4 and GATA5 is currently considered potential tumour suppressors, however, GATA6 can be used as a potential oncogene." (PMID 35488350, 2022). "Four genes (TFPI2, SOX17, GATA4, and FBN2) satisfied the criteria of “cancer-specific methylation” with high-frequency methylation in cell lines, no/undetectable methylation in normal oral mucosa, and frequent methylation in primary OSCC tumor samples." (PMID 31405379, 2019). "Both high-level GATA4 and high-level HER2 predicted DFS independently of tumor stage." (PMID 24687970, 2014). "A tumor-tissue microarray was immunohistochemically stained for HER2–4 and GATA4." (PMID 24687970, 2014). "Deletion of intestinal Gata4 and Gata6 results in an altered proliferation/differentiation phenotype, and an up-regulation of SAM pointed domain containing ETS transcription factor (Spdef), a transcription factor recently shown to act as a tumor suppressor." (PMID 24472151, 2014). "In contrast to GATA-4, tumours without MYCN-amplification exhibited higher expression values than those with MYCN-amplification (P<0.001)." (PMID 19707195, 2009).
tumor (continued). "MYCN-amplified tumours (n=32 out of 33; one specimen was not available for GATA-4 analysis) expressed significantly more GATA-4 than MYCN-nonamplified (n=218) tumours (P=0.001)." (PMID 19707195, 2009). "GATA4 was the only member of the family that showed a positive correlation between gene expression and DNA methylation at specific loci in both AA and EA patients and tumor and adjacent non-tumor tissues (left panel: right top quadrant)." (PMID 38566104, 2024). "Upon doxycycline induction, Gata4 expression in the mixed population led to robust suppression of tumor growth compared to the vehicle-treated group, indicating that Gata4 regulates tumor growth via a non-cell-autonomous mechanism." (PMID 35017504, 2022). "We find that GATA4 promotes non-cell autonomous tumor suppression in multiple model systems." (PMID 35017504, 2022). "Importantly, mechanisms that bypass senescence induction are required for tumor progression, and GATA4-dependent effects in this context would be independent of cell cycle arrest." (PMID 35017504, 2022). "GATA4 and LRP1B were tumor suppressor genes, which might be related to the resistance of olaparib." (PMID 33432021, 2021). "Among these genes, TFPI2, SOX17, and GATA4 were frequently hypermethylated in both OSCC and oral cancer patient samples in a cancer-specific manner, suggesting that these genes may play a role as tumor suppressors in OSCC." (PMID 31405379, 2019). "In recent studies, it has been demonstrated that the expression of some factors involved in gonadal development and sexual differentiation, such as GATA-4 and FOG-2, plays a role in tumor growth and progression and might represent a prognostic factor in some sex cord-derived tumors." (PMID 23029311, 2012). "However, the fact that the Rag1−/−mice or CD8 cell depleted wild-type mice used in our study are proficient in NK cell function yet fully block the effects of Gata4-induced tumor suppression suggests that, at least in this genetic context, Gata4 does not require NK cells to limit tumor growth." (PMID 35017504, 2022). "In addition to evaluating GATA4 as a potential prognostic factor, we characterized the expression levels of HER2-4, as well as gene copy numbers of HER2 in GCTs and correlated the expression levels to tumor recurrence and survival in a cohort of 80 GCT patients." (PMID 24687970, 2014). "The results indicated that the expression of GATA1, GATA4 and GATA6 remarkably varied across the tumor stages, whereas GATA2, GATA3 and GATA5 demonstrated no significantly changes in different tumor stages." (PMID 34093794, 2021). "Altogether, the lack of positive expression correlations of FOXL2 and GATA4 in the more aggressive GCTs suggests that imbalances in FOXL2-GATA4-SMAD3 expression might increase the growth potential of GCTs, leading to a more aggressive tumor behavior." (PMID 24416423, 2014). "However, it should be noted that it has been reported that in mice, nicotine promotes pancreatic carcinogenesis and tumor development via the down-regulation of GATA6, so it cannot be ruled out that GATA4 suppression may also be involved in tobacco induced carcinogenesis." (PMID 36830789, 2023).
cancer (93 papers, 2008 to 2025). A tumor composed of atypical neoplastic, often pleomorphic cells that invade other tissues. "Since GATA4 is deleted or epigenetically silenced in cancer, here we examine the role of GATA4 in tumorigenesis in mouse models through both loss-of-function and overexpression experiments." (PMID 35017504, 2022). "The GATA4 gene encodes a member of a zinc-finger transcription factors family and alterations in gene expression in this gene have been associated with cancer." (PMID 33632303, 2021). "GATA4 is considered necessary for normal pulmonary lobar development 47 and is abnormally expressed and involved in cancer-associated cellular processes in numerous malignancies 48-52." (PMID 34093794, 2021). "We further show that loss-of-function of GATA4 blunts cancer cells’ response to treatment of MEK1/2 inhibitors." (PMID 30971692, 2019). "Loss of expression and epigenetic silencing of the GATA4 gene has been reported in numerous types of cancer, including epithelial OC." (PMID 28241454, 2017). "Numerous studies gave implicated GATA4 as a tumor suppressor gene involved in tumorigenesis in various types of human cancers." (PMID 26490736, 2015). "The loss of expression of the GATA family is associated with several cancers; loss of expression for GATA-4 and GATA-5, in particular, have been reported in CRC." (PMID 22852817, 2012). "The loss of GATA4 in cancer cell lines appears also mediated by the reduction of H3 and H4 histone acetylation of the promoter locus." (PMID 19649254, 2009). "This study examined the expression of GATA 4 and GATA6 in ovarian surface epithelial cells and carcinomas in detail, and found that the loss of GATA4 is more wide spread and often precedes GATA6 in the transformation of ovarian surface epithelia." (PMID 19649254, 2009). "In addition, this work provides a collection of four metagene signatures, consisting of coding and non-coding GATA4/6 targets, with elevated diagnostic and prognostic potency for GI cancer based on analysis in a multi-cancer panel." (PMID 39456519, 2024). "The promoter methylation of GATA4 leads to the loss of its expression in many cancer types." (PMID 37372326, 2023). "Interestingly, the two cases expressing GATA4 as revealed by the pluripotent stem cell array (#14 and #15) had a well-developed stromal component that was enriched in cancer-associated fibroblasts (CAFs) expressing smooth muscle actin (SMA) and characterised by SLUG decoration." (PMID 27705913, 2016). "This heterogeneity is also consistent with the context-dependent biological roles described for GATA4 in other cancers." (PMID 41303462, 2025). "Although GATA4, GATA5 and GATA6 are known to be associated with endoderm differentiation, recent studies over few years have demystified their role in cancer progression." (PMID 41514651, 2025). "This study couples inducible RNAi-targeting of GATA4 and 6 with an integrated analysis of ChIP and RNA-seq data to molecularly dissect the cancer-related role of these lineage survival factors in GC cells." (PMID 39456519, 2024). "Numerous reports suggest GATA4’s pivotal involvement in various cancer biological processes, including apoptosis, proliferation, and metastasis." (PMID 38653973, 2024). "While the GATA4 serves many roles in various cells and tissues, our study centered on investigating its potential as a specific therapeutic target for cancer." (PMID 38653973, 2024). "Our analysis provides direct insights regarding the identification of cancer-specific lncRNA targets for GATA4/6 that are suitable for specialized diagnosis and prognosis of GC." (PMID 39456519, 2024). "Our findings showed that silencing GATA4 augmented the migratory and invasive capabilities of the cancer cells." (PMID 38653973, 2024). "Since these processes are pivotal to cancer cell metastasis, it points to the potential influence of GATA4 on the EMT by possibly modulating the ECM." (PMID 38653973, 2024).
cancer (continued). "Taken together, these data firmly establish the role of GATA4 and 6 chromatin interactions with the direct regulation of genes involved in various forms of cancer, including but not limited to GI carcinogenesis." (PMID 39456519, 2024). "GATA-binding protein 4 (GATA4) is recognized for its significant roles in embryogenesis and various cancers." (PMID 38653973, 2024). "As previously reported, KLF5 cooperates with GATA4 and 6, forming cooperative transcriptional networks that regulate downstream targets in a cancer- and tissue-specific manner." (PMID 39456519, 2024). "Another gene that showed repression was GATA4, which has been recognized as a tumor suppressor gene in different types of cancer." (PMID 37047231, 2023). "NANOG is critical in inducing and maintaining pluripotency in cancer cells thus the paralleled inhibition of GATA4 in week 1 likely reflects the enrichment of CSCs and PGCCs." (PMID 37932310, 2023). "It is notable that the top genes from an overall cancer vs control comparison included GATA4, CCDC88B, and WAS." (PMID 35202405, 2022). "We found that except for the strong staining of GATA4 in both normal and cancer tissues of the ovary, most of the GATA family members showed low expression in normal ovarian tissues, but showed moderate to high expression in OC tissues." (PMID 35488350, 2022). "Increasing studies have demonstrated that HNF4A, FOSL2, and GATA4 showed aberrant expression in various malignant tumors, playing a role in promoting or inhibiting malignancies, and our study results were consistent with these studies." (PMID 33588380, 2021). "Previous studies have found that GATA4 is a potential anti-HCC therapeutic target, the current study found that the expression of GATA4 was also decreased in cancer tissues of the most HBV-HCC patients." (PMID 34583732, 2021). "Together, our results demonstrate a prosurvival role of the p62-restricted GATA4-NF-κB axis in cancer cells adapted to acidic microenvironment." (PMID 34987705, 2021). "Compared with adjacent tissues, the high or low expression of GATA4 in cancer tissues accounted for 23.1% and 76.9%, 16.7% and 83.3% in HBV-HCC patients and in non-HBV-HCC patients, respectively." (PMID 34583732, 2021). "Nevertheless, our findings demonstrated that the upregulation of GATA4-NF-κB pathway, as a consequence of increased autophagic flux, plays a critical role for cancer cell survival under acidic environments." (PMID 34987705, 2021). "But exposure to cancer cell CM led to a significant accumulation of GATA4 in RS Spalax fibroblasts, which probably affects SASP." (PMID 31605433, 2020). "We identified 156 focal amplifications and 69 focal deletions, in well-known oncogenes, such as ERBB2, CCNE1, KRAS, MYC, EGFR, and CDK6, and cancer-related genes such as GATA4, GATA6, CD44 and ZNF217." (PMID 31570735, 2019). "We identified the transcriptional expression of 9 genes regulated by promoter hypermethylation in OSCC and finally provided 3 genes (TFPI2, SOX17, and GATA4) that were frequently hypermethylated in primary OSCC tumors in a cancer-specific manner." (PMID 31405379, 2019). "We identified that TFPI2, SOX17, and GATA4 are frequently hypermethylated in human OSCC cells in a cancer-specific manner and that the transcriptional expression of these genes is regulated by promoter hypermethylation in OSCC." (PMID 31405379, 2019). "To confirm the presence of methylation detected by NGS in CpGs 22–25 of selected region of GATA4 gene we further analyzed 124 samples (64 cancer samples and 60 control samples)." (PMID 28241454, 2017). "HDIs, TSA, depsipeptide and sodium butyrate, were shown to enhance the expression of genes such as CDKN2A, CDKN1A, SALL3, RARb2, TERT and GATA4 in human cancer cell lines by active DNA demethylation of their respective promoters." (PMID 28077797, 2017).
cancer (continued). "Other oncogenes or cancer-associated genes such as CCNE1 (19q12; O15), CD44 (11p13; Y21), CDK6 (7q21.2; Y11), GATA4 (8p23.1-p22; O19), and GATA6 (18q11.2; O17) were also located in regions with high copy number gains." (PMID 29190909, 2017). "Histone Deacetylase Inhibitors (HDIs) have been shown to activate silenced genes including CDKN1A, CDKN2A,SALL3, RARb2, TERT and GATA4, in the human cancer cells by active DNA demethylation of their respective promoters." (PMID 28077797, 2017). "GATA4 has been suggested to be a tumor suppressor gene regulated by promoter hypermethylation in various types of human cancers although the expression and promoter methylation of GATA4 in pediatric AML is still unclear." (PMID 26490736, 2015). "The expression of GATA4 varies greatly according to tissue origin, developmental timing, and cancer stage, which results in part from context-specific DNA methylation of the GATA4 promoter region." (PMID 26395571, 2015). "On the other hand, stem cell markers such as OCT4, SOX2, NANOG and GATA4 and cancer stem cell (CSC)–like markers including ALDH1A1, CD44 and CD133 were not upregulated." (PMID 25875914, 2015). "GATA4 serves as a survival factor in cancer cells by regulating the expression of anti-apoptotic Bcl-2 and Bcl-x L." (PMID 23320456, 2013). "Among the cancer drivers that show the biggest association changes between CMS2 and CMS4, we found HIF1A and CUX1, both of which are implicated in tumorigenesis and progression, and GATA4, which controls senescence." (PMID 41114645, 2025). "Having established a role for GATA4 and 6 chromatin interactions in transcriptional changes that affect cancer-related processes in GC cells, we subsequently utilized our shRNA strategies to dissect the phenotypic impact of both transcription factors both in AGS and MKN45 GC cells." (PMID 39456519, 2024). "Notably, GATA4 expression was substantially reduced in stage M1 compared to M0, suggesting lower GATA4 expression in cancer tissues with metastasis." (PMID 38653973, 2024). "Our initial step was to evaluate the pan-cancer expression of GATA4 using TIMER2.0." (PMID 38653973, 2024). "Genes related to GATA4 predominantly function in cancer metastasis pathways." (PMID 38653973, 2024). "GATA-binding protein 4 (GATA4) is reported to control cell proliferation in cancers." (PMID 35017504, 2022). "Studies have reported that GATA4 can inhibit the development of a variety of cancers." (PMID 34583732, 2021). "By sustaining Gata4/6 expression and directly controlling specific stem cell genes, Mll1 promotes stemness and prevents secretory goblet cell differentiation of Wnt-activated cancer cells." (PMID 33349639, 2020). "We found that Kras was wildtype in both GATA4-high (SH3a) and GATA4-low cancers (SH3166)." (PMID 30971692, 2019). "Many TFs, including STAT family members, serum response factors, NF-kB, and AP1, contribute to the development of various human cancers in this way, while the expression of many tumor suppressor proteins, such as GATA4 and Dickkopf-related proteins, is inhibited during carcinogenesis." (PMID 27788486, 2016). "GATA4 is abundantly expressed in various cancers and plays a crucial role in their development." (PMID 27788486, 2016). "In addition to the heart, GATA4 plays important roles in the reproductive system, gastrointestinal system, respiratory system and cancer." (PMID 26490736, 2015). "Other genes that have been identified in the sputum with aberrant methylation associated with increased risk for lung cancer include ASC/TMS1 (increased odds in cancer patients from 7.2 to 28.6), GATA4, GATA5 and PAX5β (6.5-fold increase in cancer risk with methylation of three or more genes)." (PMID 23870182, 2013).